NAT10 (N-acetyltransferase 10)
Diseases named in the same sentence as NAT10 in open-access papers (continued):
Sharing a sentence is not in itself a finding about the gene and the disease.
cancer (continued). "By modulating ac4C modifications on RNA, NAT10 influences mRNA stability and translation, playing a pivotal role in cancer development and treatment." (PMID 39764566, 2025). "Much of the recent research on NAT10 has focused on its effects on different diseases, particularly various cancers." (PMID 39817252, 2025). "Studies describing the function of NAT10 in cancer progression by acetylating a variety of substrates have been listed." (PMID 40588654, 2025). "In this study, we found that NAT10 plays a critical part in the metabolic reprogramming of cancer cells." (PMID 40303290, 2025). "In these cancers, NAT10 promotes tumorigenesis, metastasis, and chemotherapy resistance in an ac4C-dependent manner." (PMID 41316475, 2025). "The role of NAT10 in cancer progression is significant, as it contributes to cancer development through acetylating mRNAs." (PMID 41426311, 2025). "NAT10 is involved in the progression of many cancers by regulating ac4C modification, and the mechanism has been widely reported recently." (PMID 40344913, 2025). "These agents enable a more targeted approach to visualizing and treating specific cancers by exploiting the elevated NAT10 expression, making this enzyme a promising target for the development of PET radiotracers." (PMID 41369374, 2025). "In summary, our findings suggest that one of the cancer-promoting effects of NAT10 is to promote the expression of NFE2L3, form the NAT10-NFE2L3-LASP1-Akt/GSK3β axis, and promote the occurrence and progression of ccRCC." (PMID 40169553, 2025). "While NAT10 dysregulation exerts broad pathological effects across diverse diseases, its role in cancer biology represents a unique convergence of multifaceted oncogenic mechanisms." (PMID 40588654, 2025). "NAT10 inhibitor has an improved effect on the development and drug resistance of cancers, and targeting NAT10 has potential value for cancer therapy." (PMID 39817252, 2025). "Through mediating the ac4C modification of tRNA or mRNA of these genes, NAT10 enhance the translation efficiency and promote cancer progression." (PMID 40588654, 2025). "NAT10 has been reported to function essentially as a promoter of cancer development and progression." (PMID 41316475, 2025). "The regulatory mechanisms of aberrant NAT10-mediated N4-acetylcytidine (ac4C) modifications in cancer progression remains poorly understood." (PMID 39905540, 2025). "As a NAT10 inhibitor, remodelin has been shown to significantly affect cancer cells’ mitochondrial lipid metabolism through various intricate pathways, thereby altering the cells’ susceptibility to different chemotherapeutic drugs." (PMID 41310903, 2025). "Additional investigations are needed to delineate the molecular underpinnings through which NAT10 mediates metastatic progression and oncogenesis, as well as to develop strategies to effectively target NAT10 in cancer therapy." (PMID 41316475, 2025). "Here, we provide a systematic review of recent studies describing the various biological mechanisms of NAT10 and its roles in different cancers." (PMID 39817252, 2025). "We have therefore conducted a retrospective analysis of NAT10’s role in cancer, systematically integrating its cancer regulatory network to reveal its translational potential as a novel therapeutic target." (PMID 40881352, 2025). "The review summarizes nine aspects through which NAT10-mediated acetylation influences cancer progression." (PMID 40881352, 2025). "Recent studies have shown that NAT10 Khib modification at lysine 823 improves NAT10 protein stability and contributes to cancer metastasis." (PMID 39817252, 2025). "Current research has revealed that NAT10-mediated ac4C modification contributes to the pathogenesis of various diseases, including cancers, by altering gene expression patterns through site-specific ac4C modifications." (PMID 41472140, 2025).
cancer (continued). "These inhibitors significantly reduce RNA acetylation levels in cells, positioning NAT10 as a promising candidate for cancer therapy." (PMID 39976088, 2025). "Consistently, a recent outstanding study has for the first time elucidated the regulatory mechanism of NAT10 in cancer metastasis." (PMID 39764566, 2025). "This dual RNA/protein acetylation capacity positions NAT10 as a master regulator of cancer cell plasticity." (PMID 40588654, 2025). "NAT10-mediated ac4C modification has emerged as a critical driver of tumorigenesis, with elevated NAT10 expression observed in 92% of cancers and strongly correlating with poor prognosis across malignancies." (PMID 40588654, 2025). "Studying the effect of ac4C on palmitate-driven lipid accumulation uncovered that NAT10 regulates palmitate-driven FA metabolism in cancer cells in an ac4C-dependent manner." (PMID 38233930, 2024). "Existing studies have underscored the pivotal role of N-acetyltransferase 10 (NAT10) in various cancers." (PMID 38246918, 2024). "The impact of Nat10 on cancer cell proliferation has been established through its regulation of protein and RNA acetylation." (PMID 38459019, 2024). "The ac4C modification stabilizes mRNA and enhances translation, upregulating the expression of oncogenic genes and providing further insight into the cancer‐promoting functions of NAT10." (PMID 39640362, 2024). "In cancer, NAT10 is usually expressed at high levels to maintain mRNA acetylation, which in turn promotes mRNA stability and translation." (PMID 38347067, 2024). "In the following sections, we explore the specific mechanisms by which NAT10 and ac4C modifications contribute to cancer advancement in different cancer malignancies." (PMID 39640362, 2024). "As an acetyltransferase, NAT10 directly acetylates proteins involved in the initiation and progression of cancers." (PMID 39246323, 2024). "This review also summarizes the limitations and perspectives of current research on NAT10 and ac4C in cancer, to identify new therapeutic targets and advance cancer treatment strategies." (PMID 39640362, 2024). "Among various cancer patients, higher expression levels of miR-9-5p regulated by NAT10 had a shorter survival lifetime." (PMID 38308713, 2024). "We also found that miRNA processing machineries were positively correlated with NAT10 almost across all TCGA cancer types." (PMID 38308713, 2024). "Various studies imply that NAT10 regulates the expression of target genes and the biological functions of various cancers by mediating ac4C acetylation." (PMID 39251905, 2024). "Although NAT10 was identified as a substrate for Khib modification to increase its stability in promoting cancer metastasis, little is known about the other post-translational modifications on NAT10, such as lactylation." (PMID 38879723, 2024). "Serine structural domain 1 stabilizes NAT10 protein and promotes translational 4C modification in cancer via tRNA‐ac." (PMID 39640362, 2024). "Although research on NAT10 is limited, it revealed this enzyme has a key role in the development of various malignant tumors." (PMID 38233930, 2024). "Cell proliferation depends on FA metabolism genes, and exhaustion of NAT10 in cancer cells provokes a dysfunctional FA metabolism, resulting in cell death." (PMID 38233930, 2024). "Although NAT10 and ac4C modification are promising therapeutic targets for cancer treatment, there are several limitations that should be addressed." (PMID 39640362, 2024). "Our findings underscore NAT10’s oncogenic role in promoting glycolysis-immunosuppression crosstalk within cancer cells and show that NAT10-induced NPM1 acetylation enhances PD-L1 transcription and expression, strengthening immune evasion." (PMID 39648231, 2024). "Taken together, these results demonstrated that NAT10 functions by regulating miRNA production in cancers." (PMID 38308713, 2024).
cancer (continued). "Several studies have indicated that NAT10 is overexpressed in malignant tumors which correlates with poor prognosis." (PMID 39640362, 2024). "In HCC and TNBC, NAT10 is up-regulated, and its detailed mechanism in these cancers demands further research." (PMID 38233930, 2024). "NAT10 signaling pathways are involved in multiple cellular processes, including RNA modification, cell cycle regulation, metabolic reprogramming, and cancer development." (PMID 39640362, 2024). "It has been reported that Nat10 regulates the RNA translation and the behaviors of various cancer cells by enriching the ac4C modification of mRNAs21–25." (PMID 38459019, 2024). "N‐acetyltransferase 10 (NAT10)‐mediated N4‐acetylcytidine (ac4C) modification, the sole known acetylation in eukaryotic RNA, influences cancer pathogenesis and progression." (PMID 39640362, 2024). "In particular, an increase in ceramides results in apoptosis, necroptosis, autophagy, and ferroptosis in response to DNA damage agents, anti-cancer drugs, or silencing of an important cancer gene, i.e., NAT10." (PMID 37237981, 2023). "During this work, we noticed ferroptosis as one of the most negatively enriched pathways among other pathways in NAT10-depleted cancer cells." (PMID 37237981, 2023). "Previous studies have shown that mRNA ac4C regulator NAT10 plays an important role in prognosis and immune function in pan-cancer." (PMID 36765042, 2023). "NAT10, an acetylation modulator, has been proven to be a cancer-promoting gene by increasing the ac4C level." (PMID 37948132, 2023). "NAT10 regulated fatty acids metabolism in cancer cells by stabilizing fatty acid metabolic genes such as ACAT1, ACADSB, ACSL1, ACSL3, ACSL4 and ELOLV6 through ac4C RNA acetylation." (PMID 37612540, 2023). "In this study, we discovered that NAT10 depletion induces ferroptosis in cancer cells through the SLC7A11/GSH/PLOOH axis." (PMID 37237981, 2023). "As in NAT10 KD cells, the Remodelin-treated cancer cells showed a remarkable decrease in the mitochondrial respiratory genes NDUFAB1, NDUFA3, and NDUFA7." (PMID 37237981, 2023). "Here, we emphasized the critical regulatory role of mRNA ac4C modification in driving HIF‐1 mediated glycolysis addiction, identifying NAT10 as a potential therapeutic target for cancer therapy." (PMID 37328448, 2023). "Our results showed significant downregulation in expression of essential genes related to ferroptosis, namely SLC7A11, GCLC, MAP1LC3A, and SLC39A8 in NAT10-depleted cancer cells." (PMID 37237981, 2023). "Previously, evidence has shown that NAT10 is a critical player in cancer biology by regulating important cellular events such as DNA damage, cell proliferation, cell survival, and senescence." (PMID 37237981, 2023). "Taken together, the findings revealed the oncogenic role of NAT10 in initiating crosstalk between cancer cell glycolysis and immunosuppression, which can be a target for synergistic PD‐1/PD‐L1 blockade immunotherapy in CCa." (PMID 37818745, 2023). "Consistently, overproduction of oxPLs, as well as increased mitochondrial depolarization and decreased activities of antioxidant enzymes, support the notion of ferroptosis induction in NAT10-depleted cancer cells." (PMID 37237981, 2023). "Due to the important role of NAT10 in cancer progression, Remodelin has proven its anti-cancer therapeutic potential in several cancer types." (PMID 37612540, 2023). "Exposing cancer cells to DNA damage agents such as cisplatin and H2O2 causes an increase in NAT10 protein expression in a dose-dependent manner." (PMID 37237981, 2023). "First, we found that NAT10 is differentially expressed in pan-cancer and up-regulated in multiple cancer types in the UCLCAN database." (PMID 37484809, 2023). "Collectively, our results provide strong evidence of a ferroptotic event in both NAT10-depleted cancer cells and Remodelin-treated cancer cells." (PMID 37237981, 2023).
cancer (continued). "Collectively, these studies have shown that NAT10 has a metabolic impact on cancer cells by modulating lipid metabolism." (PMID 37237981, 2023). "An increase in JC-1 levels was noticed in the NAT10-deflected cancer cells, which suggests that NAT10 is critical for mitochondrial polarization and proper electron transport." (PMID 37237981, 2023). "We also analysed the expression levels of NAT10 in different types of cancer cell lines from the CCLE database." (PMID 36908042, 2023). "Overall, our results revealed that NAT10 accelerated HNSCC progression by promoting lymphatic metastasis of HNSCC, demonstrating the broad clinical importance of NAT10 in cancer metastasis." (PMID 37914704, 2023). "N4‐acetylcytidine (ac4C) modification, catalyzed by NAT10, is an important posttranscriptional modification of mRNA in cancers." (PMID 37818745, 2023). "As expected, we noticed a remarkable reduction in JC-1 as well as the cell ROS level, which suggests that the oxidative stress due to NAT10 depletion in the cancer cells is reversed due to inhibition of ferroptosis." (PMID 37237981, 2023). "Collectively, our results have provided evidence that NAT10 depletion induces ferroptosis in cancer cells." (PMID 37237981, 2023). "High ROS levels were observed in NAT10 KD cancers, suggesting NAT10 is relevant in maintaining ROS levels in cancer cells." (PMID 37237981, 2023). "Expression levels of the ferroptosis-related genes GCLC, MAP1LC3A, SLC7A11, and SLC39A8 in NAT10 KD cancer cells were significantly downregulated, therefore validating the results from our RNA-seq data." (PMID 37237981, 2023). "Although studies have reported the impact of NAT10 depletion in cancer cells, such as cell morphology, cell viability, and apoptosis, minimal information is reported on the impact of NAT10 on other types of cell death." (PMID 37237981, 2023). "Recently, we reported that N-acetyltransferase 10 (NAT10) regulates fatty acid metabolism through ac4C-dependent RNA modification of key genes in cancer cells." (PMID 37237981, 2023). "Our findings have shown that expression of GPAT4 and DGAT1 were reduced in NAT10‐depleted cancer cells and palmitate‐loaded NAT10‐depleted cancer cells suggesting that NAT10 depletion implicates in reduced lipid droplet formation." (PMID 36149760, 2022). "High‐throughput sequencing of knockdown NAT10 in cancer cells was conducted to identify enriched pathways." (PMID 36149760, 2022). "Overall, these findings suggest that NAT10 modulates lipid accumulation in cancer cells by regulating the functions of lipogenic genes." (PMID 36149760, 2022). "Further, NAT10 depletion in palmitate‐loaded cancer cells showed decrease in ac4C levels across the RNA transcripts of FA metabolic genes." (PMID 36149760, 2022). "The abnormal expression of NAT10 has been reported in several types of cancers, which is involved in various cellular activities." (PMID 36568518, 2022). "Conclusively, our results provide novel insights into the impact of NAT10‐mediated ac4C modification as a crucial regulatory factor during FA metabolism and showed the benefit of targeting NAT10 for cancer treatment." (PMID 36149760, 2022). "The examination of TCGA datasets using GEPIA webserver shows that NAT10 is highly expressed in a variety of cancers (p<0.05)." (PMID 35978804, 2022). "To study the impact of NAT10 on cancer cells, we knockdown both HeLa and MCF7 using NAT10 siRNA, which was confirmed using qRT‐PCR in transfected control (siC) versus NAT10 knockdown cells (siNAT10)." (PMID 36149760, 2022). "Notably, the overall ac4C levels of the cancer cells were significantly decreased in NAT10‐deficient cancer cells post transfected with NAT10 siRNA, suggesting that the NAT10‐deficient cancer cells have reduced ac4C levels as well as global acetylated RNAs due to NAT10‐mediated ac4C reduction." (PMID 36149760, 2022).
cancer (continued). "High‐throughput sequencing of NAT10 knockdown in cancer cells revealed fatty acid (FA) metabolism as the top enriched pathway through the Kyoto Encyclopedia of Genes and Genomes (KEGG) pathway analysis in differentially downregulated genes." (PMID 36149760, 2022). "The expression results from the cell proliferation genes supported the information that NAT10 is crucial for cancer cell proliferation and cell survival." (PMID 36149760, 2022). "Remodelin, an inhibitor of NAT10 that is primarily used to relieve nuclear lamina defect-induced phenotypes, has been demonstrated to suppress a variety of human cancer cells, inhibiting their growth and cell cycle progression." (PMID 35743017, 2022). "N-acetyltransferase 10 (NAT10) is an important regulator of mRNA acetylation in many cancers, however its function in MM is poorly studied." (PMID 35978804, 2022). "In our previous research, we revealed that either Remodelin treatment or the depletion of NAT10 inhibits the DNA replication of cancer cells, influencing the acetylation status of chromatin." (PMID 35743017, 2022). "Surprisingly, a noticeable decrease in ac4C peaks were seen in PA‐siNAT10 cancer cells via browser shots, suggesting that the genes were also modulated by NAT10‐dependent ac4C modification." (PMID 36149760, 2022). "In conclusion, we showed that NAT10 depletion reduces the expression and stability of FA metabolic genes whose functions were known to significantly impact cancer progression, metastasis, and resistance to conventional anti‐cancer treatment." (PMID 36149760, 2022). "To acquire evidence of this concept, we performed high‐throughput untargeted lipidomics in NAT10 knockdown cancer cells." (PMID 36149760, 2022). "Our study showed that NAT10 promotes FA metabolism in cancer cells by stabilising the mRNA transcripts of FA metabolic genes via ac4C mediated modification." (PMID 36149760, 2022). "Observing decreased lipid accumulation in NAT10‐depleted cancer cells, we then measured NAT10 expression levels and lipid profile in palmitate‐loaded NAT10‐depleted cancer cells." (PMID 36149760, 2022). "Results from the RT‐PCR of the lipogenic transcription factors showed significant downregulation in PA‐siNAT10 cancer cells, further providing strong evidence of NAT10 as a regulator of lipid accumulation." (PMID 36149760, 2022). "Targeting the catalyst‐dependent epitranscriptome by NAT10‐mediated ac4C occupation within target genes shows great benefits in cancer molecular therapy." (PMID 35522942, 2022). "Since NAT10 plays a significant role in cancer cell survival and viability, we then performed high‐throughput RNA sequencing to explore possible pathways associated with NAT10." (PMID 36149760, 2022). "Ac4C plays a key role in transcription and translation and disruption of its regulator, NAT10, is closely related to the occurrence and prognosis of various cancers." (PMID 36553667, 2022). "We found that ac4C peaks in the genes associated with the cancer pathway (BCL9L), the cell cycle (AKT1) and stem cell maintenance (SOX4) decreased in the NAT10 knockdown UMUC‐3 cells." (PMID 35522942, 2022). "Exogenous palmitate uptake assay was conducted to assess NAT10 knockdown cancer cells using Oil Red O staining and lipid content analysis." (PMID 36149760, 2022). "RNA‐seq data from our study showed decreased expression of ACSL1, ACSL3 and ACSL4 in NAT10‐depleted cancer cells, which further confirmed that the mRNA transcripts of these genes are controlled by NAT10‐dependent ac4C mRNA acetylation." (PMID 36149760, 2022). "Although many information point to the impact of NAT10‐dependent ac4C modification on different cancer mechanisms, knowledge of the impact of NAT10 in pathways is still obscure." (PMID 36149760, 2022). "Lipid profile analysis from NAT10‐depleted cancer cells showed a significant decrease in overall lipid content, triglycerides (TAGs), and cholesterol levels of PA‐siNAT10." (PMID 36149760, 2022).